LINC02154 (long independently transcribed non-coding RNA 2154)
Synonyms: GS1-600G8.5; MALR
Gene: Long non-coding RNA gene on chromosome X (13,266,032 to 13,308,637, reverse strand). Ensembl gene ENSG00000235385.
Diseases named in the same sentence as LINC02154 in open-access papers:
LINC02154 is named in the same sentence as 23 diseases in open-access papers, as found by Europe PMC text mining. Sharing a sentence is not in itself a finding about the gene and the disease. The quoted sentences say what the papers report.
laryngeal squamous cell carcinoma (2 papers, 2022 to 2025). A squamous cell carcinoma that arises from the larynx. "LINC02154 is a cancer-promoting factor not only in liver cancer but also in laryngeal squamous cell carcinoma." (PMID 36072656, 2022). "For instance, elevated LINC02154 expression reportedly correlates with poorer overall survival in patients with laryngeal squamous cell carcinoma (LSCC), and LINC02154 was identified as a negative prognostic factor for LSCC patients." (PMID 40529228, 2025).
kidney cancer (1 paper, 2023). Primary or metastatic malignant neoplasm involving the kidney. "We used RNA FISH technology to find out where LINC02154, AC112715.1, AC092535.5, and AC105105.3 were expressed and where they were located in kidney cancer tissue chips." (PMID 37893009, 2023).
oral squamous cell carcinoma (1 paper, 2025). "We recently showed that upregulation of LINC02154 promotes cell cycling and enhances mitochondrial function in oral squamous cell carcinoma (OSCC)." (PMID 40529228, 2025).
cancer (8 papers, 2019 to 2025). A tumor composed of atypical neoplastic, often pleomorphic cells that invade other tissues. "For instance, depletion of LINC02154 affects a number of genes involved in cancer pathways in ESCA cells, but the mechanism how LINC02154 regulate those genes is not fully understood." (PMID 40529228, 2025). "Given the critical roles of desmosomes and their components in cancer progression, our results suggest that LINC02154 may promote ESCA progression and drug resistance by interacting with desmosomal proteins." (PMID 40529228, 2025). "Given that only LINC02154 and NFE4 expression was upregulated in ccRCC and that LINC02154 has been described as a cuproptosis-linked gene and well-studied in various carcinomas including ccRCC, NFE4 was primarily focused." (PMID 38797784, 2024).
tumor (3 papers, 2023 to 2025). "Upregulated LINC02154 expression was observed in primary tumor tissues in two different ESCA cohorts." (PMID 40529228, 2025).
LINC02154 also shares sentences with these, for which no sentence is quoted: esophageal cancer (2 papers); COVID-19 (1); esophageal squamous cell carcinoma (1); hemorrhagic fever (1); hepatocellular carcinoma (1); Hodgkins lymphoma (1); infection (1); liver cancer (1); lung carcinoma (1); oral cancer (1); prostate carcinoma (1); Sepsis (1); septic shock (1); Shock (1); skin cancer (1); squamous cell carcinoma (1); thyroid cancer (1); viral infection (1).